HMGA1 (high mobility group AT-hook 1)
Diseases named in the same sentence as HMGA1 in open-access papers (continued):
Sharing a sentence is not in itself a finding about the gene and the disease.
colon carcinoma (continued). "However, the overexpression of HMGA1 has been also correlated with increased activity of trabectedin on thyroid and colon carcinoma cells, suggesting that the prognostic of HMGA1 may depend on the type of malignancy." (PMID 38758230, 2024). "Interestingly, a weak immunoreactivity was observed in normal colon mucosa after staining with antibodies raised versus BUBR1 and TTK, whereas colon carcinoma samples showed a strong immunoreactivity that significantly correlated with HMGA1 staining (p = 0.006 for BUBR1 and p < 0.001 for TTK)." (PMID 26009897, 2015). "In addition, HMGA1 is among the most enriched genes in colon cancer compared to normal mucosa." (PMID 22276142, 2012). "HMGA1 directly induces ASCL2 by binding to its promoter and recruiting activating histone marks in human colon cancer cells." (PMID 39895630, 2025). "Luo and colleagues demonstrated that HMGA1 is directly bound to the ASCL2 promoter and activated ASCL2 expression in human colon cancer cells." (PMID 39895631, 2025). "Because the repressive histone 3 lysine 27 trimethyl (H3K27me3) was identified in a colon cancer cell line (HCT116) from a public database (GSE171817), we assessed its binding relative to that of HMGA1." (PMID 39895630, 2025). "When SIRT1-Flag tagged expression plasmid was transfected into Human colon cancer HCT116 cell line, the acetylation levels of SMARCA5, MTA2, HMGA1, EGFR, CHD4 and GOT2 decreased as equal amounts of the proteins were immunoprecipitated." (PMID 28676654, 2017). "It is noteworthy that a stronger correlation between HMGA1 and SAC gene mRNA expression was found when liver metastases from colon carcinomas (n = 185) were analyzed by Illumina array." (PMID 26009897, 2015). "An oncogenic function of HMGA1 and IGF2BP1 has been reported in other cancers, including colon cancer, with evidence that both factors enhance tumorigenesis." (PMID 26244988, 2015). "We found that enforced overexpression of HMGA1 in human colon carcinoma cells GEO, sensitive to CTX and expressing low levels of HMGA1, promoted resistance to CTX and 5FU." (PMID 25409711, 2014). "In summary, our studies provide the first evidence linking HMGA1 to cellular properties and transcriptional networks important in stem cells, EMT, and metastatic progression in colon cancer." (PMID 22276142, 2012). "Restoration in ASCL2 levels results in a partial rescue of proliferation and full rescue of clonogenicity in both cell lines, suggesting that ASCL2 mediates some, but not all, effects of HMGA1 in these colon cancer cells." (PMID 39895630, 2025). "Together, our results establish HMGA1 as an epigenetic gatekeeper of ASCL2 and Wnt signals, inflammation, and a stem-like state in colon cells with APC inactivation, highlighting HMGA1 as a promising potential therapeutic target in colon cancer." (PMID 39895630, 2025). "Most importantly, both HMGA1 and ASCL2 are coexpressed and upregulated in human colon cancer." (PMID 39895630, 2025). "To determine if HMGA1 activates the ASCL2 promoter, we cloned the human ASCL2 promoter sequence (–2.5 kb from the TSS) upstream of the luciferase reporter gene and transfected this construct into colon cancer cell lines (SW620, SW480)." (PMID 39895630, 2025). "Intriguingly, HMGA1 protein levels increase within the colon tumors compared with nontumor colon epithelium, even in the setting of Hmga1 haploinsufficiency." (PMID 39895630, 2025). "Because our results strongly link HMGA1 to ASCL2 in colon tumorigenesis in humans and mice, we tested whether HMGA1 directly activates ASCL2 expression in human colon cancer cells." (PMID 39895630, 2025). "To determine whether ASCL2 restoration will rescue these phenotypes, we reexpressed ASCL2 in both colon cancer cell lines (SW620 and SW480) with HMGA1 silencing." (PMID 39895630, 2025). "HMGA1 upregulates ASCL2 and promotes oncogenic properties in human colon cancer cells." (PMID 39895630, 2025).
colon carcinoma (continued). "HMGA1 is also highly up-regulated in colon cancer compared with nonmalignant epithelium, and SOX9 becomes overexpressed during colon carcinogenesis." (PMID 35328637, 2022). "Notably, we have found a strong correlation between HMGA1 and BUBR1 and TTK protein levels in human colon carcinomas." (PMID 26009897, 2015). "Moreover, we examined the sensitivity to these drugs of the colon carcinoma cell line, SW48, which expresses low HMGA1 levels, transfected with HMGA1 (SW48-HMGA1)." (PMID 25409711, 2014). "To this end, we assessed three-dimensional colonosphere formation in the colon cancer cell lines with or without knock-down of HMGA1." (PMID 22276142, 2012). "Indeed, as previously reported, HMGA1 expression was abundant in the colon carcinoma samples, whereas it was not detectable in normal colonic mucosa." (PMID 26009897, 2015). "While HMGA1 drives clonal expansion, aberrant differentiation, and transformation in diverse settings, its function in colon tumorigenesis has not been studied in detail despite the fact that it is among the most overexpressed genes in colon cancer compared with nonmalignant epithelium." (PMID 39895630, 2025). "As we previously reported, HMGA1 and SOX9 are upregulated in colon cancer compared with nonmalignant epithelium." (PMID 39895630, 2025).
glioblastoma (21 papers, 2013 to 2024). The most malignant astrocytic tumor (WHO grade IV). "Furthermore, a series of studies have proposed that the impaired expression of HMGA1 in glioma cells may be linked to gliogenesis and confer a survival benefit to mesenchymal glioblastoma stem-like cell (GSC) tumors." (PMID 37226244, 2023). "In glioblastoma multiforme, HIF1A-AS2 acts as a protein scaffold facilitating interactions with co-partners IGF2BP2 and DHX9, leading to the maintenance of mesenchymal glioblastoma stem-like cells in hypoxic niches by activating HMGA1 expression." (PMID 38920249, 2024). "In diffuse astrocytoma and glioblastoma, strong cytoplasmic and nuclei staining for HMGA1 protein was observed, whereas only slight nuclear HMGA1 expression was detected in NB." (PMID 34887392, 2021). "In glioblastoma cells HMGA1 maintain stemness by modifying the chromatin status and favoring transcription of stemness promoting genes." (PMID 31963852, 2020). "Upregulation of HMGA1 in glioblastoma positively correlates with malignancy, angiogenesis, and invasion." (PMID 24564251, 2013). "HMGA1 silencing reduces the stemness of glioblastoma and restores temozolomide sensitivity." (PMID 35864955, 2022). "Furthermore, HIF1A-AS2 directly binds to insulin-like growth factor 2 mRNA binding protein 2 (IGF2BP2)/ATP-dependent RNA helicase A (DHX9) proteins, resulting in increased expression of HMGA1, formation of glioblastoma stem-like cells, and adaptation to hypoxia in the tumor microenvironment." (PMID 34557530, 2021). "For instance, HIF1A-AS2 promotes the expression of HMGA1 through interactions with IGF2BP2 and DHX9, aiding glioblastoma stem-like cells (GSCs) in adapting to hypoxia within the tumor microenvironment." (PMID 39416790, 2024). "For example, HMGA1 was not only high expressed in human ESC, but also can reduce stemness of glioblastoma stem cells by its silence." (PMID 35313979, 2022). "For example, the HMGA1 promoter contains an E2F binding site and three putative SP1 binding sites; in T98G glioblastoma cells, E2F1 binds to the HMGA1 promoter and cooperates with SP1 to regulate HMGA1 transcription." (PMID 31963852, 2020). "Previous reports in glioblastoma showed that HIF1A-AS2 interacts with proteins IGF2BP2 and DHX9 while enhancing the expression of their targets such as high mobility group AT-hook 1 (HMGA1)." (PMID 32756406, 2020). "A previous study showed that HIF1A-As2 modulates glioblastoma stem-like cell proliferation, self-renewal and hypoxia-dependent molecular reprogramming by interacting with DHX9 and further influencing downstream target HMGA1." (PMID 37041291, 2023).
Insulin resistance (21 papers, 2008 to 2025). Increased resistance towards insulin, that is, diminished effectiveness of insulin in reducing blood glucose levels. "Abnormal expression of HMGA1 is closely associated with tumors, cardiovascular diseases, insulin resistance and T2DM, as well as nervous system diseases." (PMID 33750458, 2021). "Recently, the transcription factor high-mobility-group AT-hook 1 (HMGA1) has been linked to NF-kB activation, and involved in inflammation and in the pathogenesis of insulin resistance." (PMID 30674322, 2019). "The HMGA1-p was found overexpressed in diabetic patients then causing a significant destabilization of HMGA1 mRNA with consequent loss of INSR expression, which is regulated by HMGA1, then generating the insulin resistance phenotype." (PMID 26895108, 2016). "In this context, a new rare variant, rs146052672, which consists of a C insertion at position −13 of exon 6 (c.136-14_136-13insC) of the HMGA1 gene has been recently associated with increased risk of insulin resistance and T2D." (PMID 26296198, 2015). "Thus, whereas HMGA1 gene defects associate with insulin resistance and diabetes in humans and mice, HMGA1 overexpression in adipose tissue prevents insulin resistance in mice." (PMID 27445976, 2016). "Moreover, aberrant expression of Hmga1 was found to cause insulin resistance." (PMID 37542675, 2023). "In other two patients (mother and daughter) with the type A syndrome of insulin resistance, a hemizygous deletion of the HMGA1 gene was also identified." (PMID 30034366, 2018). "As insulin resistance plays a pivotal role in the pathophysiology of metabolic syndrome, the impact of HMGA1 has been investigated in two large Italian and Turkish populations, both affected by metabolic syndrome." (PMID 30034366, 2018). "As Lin28a directly promotes HMGA1 translation, it has been postulated that in muscle-specific Lin28a knockout mice, insulin resistance is, at least in part, due to reduced HMGA1 levels and consequently impaired INSR expression." (PMID 30034366, 2018). "HMGA1 has a wide range of roles in insulin resistance, glucose homeostasis, lipid metabolism, and atherosclerosis, and has recently been proposed as a convincing molecule involved in the pathological features of overlapping two diseases, PCOS and cardiovascular disease." (PMID 36406137, 2022). "In addition, Esposito and co-workers found seven pseudogenes homologous to the high mobility group AT-hook 1 (HMGA1) gene, which is associated with insulin resistance and carcinogenesis." (PMID 27936183, 2016). "It is tempting for us to speculate that, by binding to the 3′UTR of the HMGA1 mRNA and facilitating the decay of transcript, increased levels of hsa-miR-1225-3p could produce a down-regulation of the insulin receptor expression and insulin resistance." (PMID 37510186, 2023). "Interestingly, the absence of HMGA1 proteins was shown to cause insulin resistance and diabetes in humans and mice." (PMID 18651940, 2008). "Thus, taken together, our findings consistently support the role of HMGA1 as a key element in the transcriptional regulation of genes involved in glucose metabolism and add new insights into the compensatory mechanisms that may contribute to counteract insulin resistance in vivo." (PMID 19460132, 2009). "Restoration of HMGA1 protein expression in these subjects' cells enhanced INSR gene transcription and restored cell-surface INSR protein expression, thus confirming that defects in HMGA1, by decreasing INSR protein production may indeed induce severe insulin resistance." (PMID 30034366, 2018).
glioma (18 papers, 2013 to 2025). A benign or malignant brain and spinal cord tumor that arises from glial cells (astrocytes, oligodendrocytes, ependymal cells). "The results confirm the differential expression of many transcriptional regulatory proteins that have been already implicated in the pathogenesis of gliomas (HMG proteins -HMGA1, B1 and B2) as well as revealing some novel proteins (NUCKS1 and SON) discussed here." (PMID 31358880, 2019). "One recent study found that lncRNA HIF1A-AS2 interacted with IGF2BP2 and DHX9 to stabilize HMGA1 mRNA 46, and HMGA1 has been shown to promote glioma malignant progression by activting the PI3K/Akt/c-Jun signaling pathway." (PMID 37063420, 2023). "As an inhibitor of glioma, miR-1297 can also target and negatively regulate HMGA1 to reduce cell viability." (PMID 35864955, 2022). "These genes include HMGA1 in glioma, AKT1 in glioma, PTC, GC, and HCC, HEMGN in PTC, APLN and MMP19 in GC, WNT1 in CRC, NUPR1 in CRC and OSCC, LY6E and CTSB in CHOL, KLK4 and PLXNB2 in OC, and HDAC4 and STAT3 in SaOS." (PMID 36175921, 2022). "It is upregulated in gliomas and correlates with patient survival; moreover, knockdown of HMGA1 suppresses the stemness of glioma stem cells and increases their sensitivity to temozolomide (TMZ)." (PMID 34887392, 2021). "Using Kaplan–Meier analysis and the log-rank test, HMGA1 expression, MYH9 expression, age, pathological diagnosis, and WHO grade were found to be significantly associated with the overall survival of glioma patients in univariate analysis (both P < 0.05)." (PMID 34887392, 2021). "In accordance with these studies, we have found that HMGA1 promoted glioma cell proliferation, invasion, and migration, suggesting that it is a key regulator of the EMT process." (PMID 34887392, 2021). "Immunofluorescent detection of MYH9 and β-catenin was performed on glioma cells overexpressing HMGA1; we observed increased cytoplasmic expression of MYH9 and total expression of β-catenin." (PMID 34887392, 2021). "In U87MG glioma cells, overexpression of either HMGA1 or HMGA2 or both significantly enhances luciferase activities driven by the two promoters." (PMID 27259253, 2016). "Moreover, the stemness and temozolamide resistance of glioma cells also decreased after HMGA1 silencing." (PMID 35864955, 2022). "Through regulating HMGA1, miR-1297 inhibited glioma cell growth in vivo and in vitro." (PMID 36183123, 2022). "Based on this, we further confirmed that HMGA1 inhibition sensitizes glioma cells to TMZ." (PMID 34887392, 2021). "Recent studies have suggested the important roles of HMGA1 in gliomas." (PMID 34887392, 2021). "Functionally, HMGA1 was found to promote glioma cell growth in vivo and in vitro." (PMID 34090483, 2021). "In the present study, we revealed that HMGA1 and MYH9 were upregulated in gliomas and their expression correlated with WHO grade, and HMGA1 promoted the acquisition of malignant phenotypes and chemoresistance of glioma cells by regulating the expression of MYH9 through c-Jun-mediated transcription." (PMID 34887392, 2021). "In our previous work, we demonstrated that overexpressed HMGA1 promoted proliferation, invasion, and migration in glioma cells, and Vimentin could directly bind to HMGA1." (PMID 34887392, 2021). "Although we have previously identified an oncogenic ZEB2/miR-637/HMGA1 signaling axis targeting Vimentin which could promote both migration and invasion in glioma, little is known about the role of HMGA1 which is worthy of continuous investigation." (PMID 34887392, 2021). "An involvement of miR-1297 has been reported in the deregulation of the glioma that may prevent proliferation and invasiveness by targeting HMGA1." (PMID 28115593, 2017). "However, we did not observe that HMGA1 mRNA was significantly reduced after GSCAR knockdown in GSCs, suggesting that HMGA1 could be regulated either by IGF2BP2 or DHX9 in glioma tumor cells in different cellular contexts." (PMID 37063420, 2023).
glioma (continued). "This lymphoid-focused pattern was conserved in glioma, LIHC, and CRC, with consistent HMGA1 detection in Tregs and exhausted CD8+ T cell populations." (PMID 41463532, 2025). "Subsequently, the data for HMGA1 and MYH9 mRNA expression in gliomas were extracted from the Chinese Glioma Genome Atlas (CCGA) database." (PMID 34887392, 2021). "Our study demonstrated that both HMGA1 and MYH9 promote glioma cell proliferation, invasion, migration, and TMZ resistance." (PMID 34887392, 2021). "Our data tend to provide new insights into the molecular function of HMGA1 and MYH9 as well as its regulatory mechanisms in gliomas." (PMID 34887392, 2021). "In primary glioma tissues from our department, both HMGA1 and MYH9 were upregulated in glioma samples compared to NB tissues." (PMID 34887392, 2021). "IHC revealed that the protein expression of HMGA1 and MYH9 also was increased in glioma tissues compared with NB." (PMID 34887392, 2021). "Recently, the markers of glioma stem cell that are studied more than others include CD133, nestin, HMGA1, A2B5, etc.." (PMID 25967234, 2015). "These miR-637-targeted genes include HMGA1, CDK6, and WNT7A in glioma, HEMGN in PTC, APLN in GC, USP21 in HCC, LY6E and CTSB in CHOL, NUPR1 in OSCC and MM, HDAC4 in SaOS, ABL1 in CML, KLK4 in OC, PLXNB2 in OC, AKT1 in TNBC, PTC, and HCC, AKT3 in TNBC, and RING1 in CCa." (PMID 36175921, 2022). "QPCR showed that both HMGA1 and MYH9 mRNA levels were upregulated in glioma tissues compared to normal brain tissues (NB), and overexpressed levels of HMGA1 and MYH9 in glioma patients were positively correlated with pathological classification (WHO 2 vs. WHO 3 vs. WHO 4) (P < 0.05)." (PMID 34887392, 2021). "In contrast, IL33oe increased H2A and H3 proteins and HMGA1 and HMGA2 in glioma cells." (PMID 34744630, 2021). "To confirm whether HMGA1 modulating of MYH9 was responsible for the promotion of the proliferation, migration, and invasion of glioma cells, we utilized an MYH9-overexpression vector in shHMGA1 glioma cells." (PMID 34887392, 2021). "Further multivariate analysis demonstrated that WHO grade, HMGA1, and MYH9 expression significantly correlated with patient survival (P = 0.01, P = 0.002, and P < 0.001, respectively), indicating that these three factors should be treated as independent prognostic factors in patients with glioma." (PMID 34887392, 2021). "Therefore, HMGA1 and MYH9 play essential roles in gliomas, which should be considered as tumoral enhancers with significant value as unfavorable progression indicators for patients with glioma, and may serve as feasible therapeutic targets in the future." (PMID 34887392, 2021).